STC1 (stanniocalcin 1)
Diseases named in the same sentence as STC1 in open-access papers (continued):
Sharing a sentence is not in itself a finding about the gene and the disease.
tumor (continued). "Several of these HSEPs have been reported in other contexts to play key roles in tumour progression by cancer cell proliferation (NRSN2, WISP2, SPRX1, LCK), metastasis (GOLM1, STC1, MGAT5B), and stemness (STC1, TMEM59), as well as promoting angiogenesis (ANGPTL4) and host immunosuppression (CD70)." (PMID 33050615, 2020). "Since a faster rate of ATP production is essential to support cancer growth and metastasis, the present study identified the effect of STC1-overexpression on reducing energy metabolism, leading to an activation of AMPK pathway but an inhibition of p70S6K/p-rpS6 signaling to reduce tumor growth." (PMID 29467934, 2018). "In contrast, STC1 protein expression correlated with fewer features of tumor progression and was not an independent or significant prognostic factor for OS in LSCC." (PMID 24743310, 2014). "STC1 and STC2 are involved in tumor progression and metastasis." (PMID 24743310, 2014). "STC1 and STC2 were expressed predominantly in the cytoplasm or on the membranes of tumor cells." (PMID 24743310, 2014). "STC1 and STC2 are involved in various biological mechanisms of tumor progression." (PMID 24743310, 2014). "A distinct differencet in STC1 staining was observed between tumour and non-tumour tissue." (PMID 39103836, 2024). "Specifically, STC1 could damage the phagocytosis of antigen presenting cells (APC) and the activation of T cells by capturing calreticulin (CRT), thereby blocking the “eat me” signal of tumor cells and mediating tumor immune escape." (PMID 39654892, 2024). "Studies have shown that STC1 was secreted by CAFs and suppressed macrophage differentiation by binding to glucose-regulated protein 94 (GRP94), suggesting that STC1 exhibited an essential influence on tumor macrophages differentiation and participated in tumor immunity." (PMID 39654892, 2024). "Given the vascular and tumor location of CALR/STC1, systemic administration may suffice but may not reach the infiltrating edge." (PMID 38786045, 2024). "IHC staining of these xenograft tumours for previous stem cell-like markers, compared to the control xenograft tumours, showed that the percentage of CD44, NANOG, SOX9, SOX2 positive cells was reduced in the STC1-silenced group, and STC1 shRNA and circUBA2 co-transfection played a reversal role." (PMID 39103836, 2024). "STC1 may influence CD4+ T cells to secrete cytokines, including IL-17, IL-31, and IL-33, which modulate immune responses via autocrine or paracrine mechanisms, thereby either amplifying or suppressing immune activity within the tumor microenvironment." (PMID 39201771, 2024). "STC1 may influence the infiltration and activity of CD8+ T cells and CD4+ T cells by modulating pro-inflammatory or immunosuppressive factors, such as TGF-β, within the tumor microenvironment." (PMID 39201771, 2024). "In addition, STC1 also activates ERK and JNK pathway promoting inhibitor of apoptosis proteins (BcL-2 and BcL-xl) and inhibits the expression of pro-apoptotic proteins (Bax, Bak and Bid) for tumor survival." (PMID 38215156, 2024). "Similar studies showing that STC1 did not affect tumor proliferation have been reported." (PMID 37400459, 2023). "Although STC1 plays a pro‐oncogenic role in tumour progression, the counteracting effects STC1 on the pro‐inflammatory effects of IL6 and IL8 might slow down the process of carcinogenesis as the tumour grows." (PMID 32468698, 2020). "Clinical data have also revealed that STC1 may have a negative correlation with prognosis, a higher STC1 expression level in tumour tissues was correlated with shorter DFS (disease‐free survival) and OS (overall survival)." (PMID 32468698, 2020). "However a negative correlation (p = 0.008, 216 patient samples) of STC1 expression with tumor size was observed." (PMID 29467934, 2018). "In the remaining 140 cases (61.1%), staining for STC1 was negative throughout the tumor tissue." (PMID 22200953, 2012).
tumor (continued). "In the up regulated category this increase is represented by the expression of hypoxia related gene Stc1, which increased to a FC value 55.9 in F111 NA16 cells, dropped below the FC value > 2.0 in colony derived cells and again increased to FC value 48.4 in tumor derived cells." (PMID 21122158, 2010). "Furthermore, the localization pattern of STC-1 in the epithelium may suggest that this protein is involved in the epithelial-mesenchymal transition (EMT) process, thus, playing a crucial role in the initiation of the tumor microenvironment." (PMID 34650342, 2021). "Both FAP and STC1 mRNA levels were increased in C2‐cocultured PF, while FAP mRNA upregulation was also detected in miR‐27a knockdown fibroblasts, confirming their activation and further supporting our hypothesis of tumour cell‐derived activation of fibroblasts." (PMID 32133790, 2020). "On the other hand, other parameters listed in Table I (age, gender, tumor location, number of metastatic lymph nodes, ly status, v status, pStage and with or without NAC) did not correlate with STC1 expression." (PMID 22200953, 2012). "This analysis demonstrated an increase in the number of SPC+ cells that mainly represent tumor cells derived from AT2 cells in the Stc1−/− SPK lung, although this difference was not significant when adjusted for lung weight, reflecting the close relationship between tumor burden and lung weight." (PMID 32579928, 2020).
cancer (110 papers, 2007 to 2025). A tumor composed of atypical neoplastic, often pleomorphic cells that invade other tissues. "STC1 is located on human chromosome 8p21.2, which frequently exhibits alterations in a number of cancers, suggesting that STC1 is associated with the development of tumors." (PMID 41020346, 2025). "STC1 has higher expression in cancer stroma and cancer associated fibroblasts (CAFs) than normal stroma and normal fibroblasts (NFs)." (PMID 39654892, 2024). "By examining the roles of key genes associated with high-altitude diseases across various cancers, researchers can achieve a more thorough understanding of STC1’s functions under diverse physiological and pathological conditions." (PMID 39201771, 2024). "This underscores the potential of STC1 as a diagnostic, prognostic, and therapeutic target in cancer." (PMID 39186548, 2024). "The ROC curve was used to assess the pan-cancer diagnostic value of STC1 from these eight GEO datasets." (PMID 39201771, 2024). "Understanding the role of the key gene STC1 in cancer, which is also implicated in high-altitude diseases, can aid doctors and researchers in developing more precise treatment strategies." (PMID 39201771, 2024). "Staniocalcin-1 (STC1), a glycoprotein, is associated with the proliferation of stem cells and progenitor cells and can affect and regulate cancer stemness." (PMID 37004088, 2023). "Some studies had shown that the relative expression level of the STC1 gene in cancer tissues was higher than that in adjacent normal mucosa; the high expression of STC1 was associated with a low postoperative survival rate." (PMID 35252182, 2022). "Collectively, these findings confirm that weak cellular accumulation of STC-1 is associated with more aggressive cancer outcomes, which is consistent with our data." (PMID 34650342, 2021). "Although identified as stromal, STC1 is also expressed by the epithelial cells, well-differentiated cancer cells and cancer-associated stromal cells." (PMID 34911496, 2021). "These evidences suggest that STC1 is a potential diagnostic and prognostic marker as well as therapeutic target of cancer." (PMID 32468698, 2020). "Stanniocalcin-1 (STC1) is a secreted glycoprotein implicated in several pathologies, including inflammation and cancer." (PMID 32286381, 2020). "The secretion of STC1 is intermittent and can be stimulated by external stimulus, and thus, the secretion of STC1 is more susceptible to external cytokines related to cancer." (PMID 32468698, 2020). "Despite the current evidence shows an association between STC1 and cancer progression, further investigation is necessary to reveal at the mechanistic perspectives of its actions and effects on carcinogenesis." (PMID 26469082, 2015). "Stanniocalcin-1 (STC-1) is a glycoprotein hormone implicated in the progression of various cancers." (PMID 39071498, 2024). "Moreover, we visualized the association of STC1 expression with different immune subtypes of eight cancer types, including BLCA, BRCA, COAD, KIRC, LUAD, MESO, OV, and STAD." (PMID 39201771, 2024). "Additionally, high STC1 expression is associated with poor prognosis and reduced survival rates in cancer patients, making it a potential biomarker for cancer progression and a target for therapeutic intervention." (PMID 39668832, 2024). "We suspected that STC1 may cause cancer by influencing many processes that are linked with tumors, including cell proliferation, survival, migration, and invasion." (PMID 39201771, 2024). "Targeting STC-1 and its interaction with calreticulin may be an approach to enable patients to be susceptible to cancer immunotherapy." (PMID 36882399, 2023). "Several studies have shown that STC1 is associated with cancer development." (PMID 32286381, 2020).
cancer (continued). "We showed that expression of HIF-1alpha and its downstream target STC1 are upregulated in PGCCs or budding cells, and this expression is associated with several cancer stem cell markers such as CD44, OCT3/4, and Nanog and several EMT-inducing transcription factors, including Twist-2 and Snail." (PMID 24348907, 2013). "There is mounting evidence that STC1 is tightly associated with the development of cancer." (PMID 23382863, 2013). "However, the mutation level with STC1 is low in most cancers." (PMID 39201771, 2024). "However, the results are sometimes contradictory and the underlying mechanisms of the interaction of STC1 and cancers remain unclear." (PMID 32468698, 2020). "We first found that knockdown of STC1 inhibited the NF‐κB pathway in GBM cells, which was consistent with studies of STC1 in other cancers." (PMID 41020346, 2025). "The role of STC1 in the activation of the NF‐κB pathway has been widely demonstrated in a variety of cancers." (PMID 41020346, 2025). "Stanniocalcin‐1 (STC1) is a glycoprotein hormone involved in multiple biological processes in cancer cells." (PMID 41020346, 2025). "Several observations support a potential role for STC1 in the progression of advanced carcinoma and as a potential biomarker for chemotherapy-resistant disease." (PMID 39807836, 2025). "We extracted STAD from TCGA and non-carcinoma sample data from GTEx, analyzed STC1 expression difference between the two groups, and discovered the high expression of STC1 within GC tissues (P = 6.8e-37)." (PMID 40741411, 2025). "Collectively, these newly found players shed light on the mechanisms of eATP-induced as well as STC1- and V-ATPase-mediated drug resistance and offer potential novel targets for combating drug resistance in cancers." (PMID 38380370, 2024). "There is a significant (p < 0.05) association between the levels of STC1 expression and TMB in ten different forms of cancer." (PMID 39201771, 2024). "By constructing STC1 over-expression cell to further explore its mechanism, it was found that STC1 secreted by cancer cell promoted the transformation from NFs into CAFs, but detailed mechanisms were not be clarified." (PMID 39654892, 2024). "It was indicated that STC1 expression differed in immune subtypes in 30 cancers, while its expression differed in molecular subtypes in 17 cancers." (PMID 39201771, 2024). "Activated STAT3 forms dimers and targets genes like Cyclin D1, survivin, MMP-7, OPG, and STC-1 in cancer cells." (PMID 38881902, 2024). "In humans, STC1 is widely expressed across various tissues and plays roles in multiple physiological and pathological processes, including cancer development." (PMID 39668832, 2024). "To clarify STC1 mRNA expression in different pan-cancer cell types, we obtained single-cell RNA sequencing data for BRCA, CHOL, KIRC, and STAD from GEO datasets for analysis." (PMID 39201771, 2024). "During our research, we explored the correlations between STC1 differential expression and pan-cancer immune subtypes and molecular subtypes from the TISIDB database." (PMID 39201771, 2024). "The PI3K/Akt pathway is a critical regulator of cancer metabolism, and our data confirmed that STC-1 ablation suppresses this pathway in OSCC cells." (PMID 39071498, 2024). "Since cytoskeleton remodeling and EMT play roles in drug resistance in cancer cells, it can be inferred that STC1 also plays roles in the drug resistance." (PMID 38380370, 2024). "In this study, the STC1 gene was strongly expressed in 13 types of cancer but had only low expression in KICH and KIRP." (PMID 39201771, 2024). "To further study the latent role of STC1 in cancer, we investigated the function of STC1 at the single-cell level using the CancerSEA database." (PMID 39201771, 2024). "The overexpression of mesenchymal genes, such as VIM or STC1, suggests that the MM ECs undergo EMP or endothelial–mesenchymal transition (EndMT), a process often associated with cancer progression." (PMID 39596117, 2024).
cancer (continued). "The consistent overexpression of STC1 across cancer tissues, as observed in multiple datasets, combined with its association with poor prognosis, underscores its potential as both a biomarker and a therapeutic target." (PMID 39668832, 2024). "We also explored the relationship between STC1 expression and different molecular subtypes in eight cancer types." (PMID 39201771, 2024). "We concluded that the mRNA expression and protein levels of STC1 in some forms of cancer are connected to the patient’s stage of the disease." (PMID 39201771, 2024). "STC1 expression in the majority of cancer tissues showed weak to moderate cytoplasmic positivity with distinct extracellular staining." (PMID 39201771, 2024). "This study focuses on the role of the STC1 gene in high-altitude diseases and explores its expression patterns in different types of cancer." (PMID 39201771, 2024). "By doing a survival analysis, we estimated the correlation between STC1 expression and the outcome of patients who were included in the pan-cancer dataset by using forest plots, including OS, DPS, and PFI." (PMID 39201771, 2024). "The results of this study provide mechanistic insights on how eATP, STC1, and V-ATPase induce and regulate drug resistance and identify potential novel therapeutic targets for combating drug resistance in cancer." (PMID 38380370, 2024). "Proof-of-concept genetic knock-down of STC1 decreases cancer cell growth, and several miRNAs targeting STC1, such as miR-606 and miR-146-5p, have been exploited for therapeutic purposes in preclinical models." (PMID 38786045, 2024). "In contrast to its function in most cancers, high expression of STC-1 in other diseases promotes survival." (PMID 36882399, 2023). "STC1 is a glycoprotein that functions as a paracrine/autocrine factor involved in many physiological/pathological pathways that promote cancer cell viability, migration, proliferation, invasion, and chemoresistance." (PMID 36795484, 2023). "It has been shown in various cancer studies that stanniocalcin-1 (STC1) is secreted by CAFs, however, its function in HCC is still not clear." (PMID 37004088, 2023). "The expression and secretion of STC1 in cancer tissue can be stimulated by external stimuli, including external cytokines and oxidative stress." (PMID 36779699, 2023). "Considering the pleiotropic role of STC1, especially its intercellular linkage between MSCs, cancer cells, and macrophage stimulation, it is interesting to know what role it plays in connection to the functions of MSC in TME." (PMID 36779699, 2023). "Despite our knowledge that a variety of cells can secrete STC1, the functions of secretory STC1 in cancer remains poorly understood." (PMID 37400459, 2023). "Using RNAi technology and neutralizing Abs, we discovered that ANGPTL4 and STC1 differentially regulated cancer-associated mesothelial cell tumor-promoting functions, and that neutralization of ANGPTL4 alone or in combination with STC1 prevented metastasis." (PMID 36795484, 2023). "STC1, secreted glycoprotein stanniocalcin-1, is the mediator of metastasis by platelet-derived growth factor (PDGF) related to cancer-associated fibroblasts (CAF) in CRC." (PMID 38036953, 2023). "Since lipids are necessary elements in OC metastasis and provide cancer cells with energy, we demonstrated that STC1 promoted lipid metabolism by regulating lipid-related genes." (PMID 35392966, 2022). "The RT-qPCR assay showed upregulation of MIAT and STC1 while downregulation of hsa-miR-532-3p expression in cancer." (PMID 35607443, 2022). "An increasing body of evidence suggests that the dysregulation of STC1 was strongly correlated with multiple physiological and pathophysiological processes, including cancer." (PMID 35927233, 2022). "While STC1′s multiple roles in cancer growth, metastasis, and EMT have been reported in other cancer cell lines, this is the first time that STC1′s role in CSC formation has been studied and described." (PMID 36499099, 2022).